NLRP3 (NLR family pyrin domain containing 3)
Diseases named in the same sentence as NLRP3 in open-access papers (continued):
Sharing a sentence is not in itself a finding about the gene and the disease.
COVID-19 (continued). "In addition, NLRP3 activation has been demonstrated in postmortem lung tissue of COVID-19 patients, a condition that could modify the NLRP3 expression and activation." (PMID 36498845, 2022). "Therefore, targeting NLRP3 might be helpful in diminishing damage of HSPCs and EPCs during COVID-19 pathogenesis." (PMID 36263178, 2022). "A recent animal study showed that remdesivir may be nephroprotective in COVID-19 via effective inhibition of inflammatory immune responses, which specifically repress NLRP3 inflammasome activation in lipopolysaccharide (LPS)-activated macrophages in mice models." (PMID 35683518, 2022). "However, to our knowledge, there is no data on NLRP3 expression and activation in airway tissue of live COVID-19 patients and no data regarding the association of the airway NLRP3 inflammasome and COVID-19 severity and mortality." (PMID 36498845, 2022). "Interestingly, NETosis was also shown to activate pyroptosis, through induction of NLRP3, suggesting that during COVID-19 NETosing neutrophils might also contribute to IL1-β and IL-18 secretion." (PMID 35244141, 2022). "Thus NLRP3 inflammasome overactivation may be responsible for SARS-CoV-2 induced cytokine storm in COVID-19 patients." (PMID 34150848, 2021). "Therefore, we hypothesized that uncontrolled oxidative stress may form a positive feedback loop exacerbating NLRP3-inflammasome activation and the production of pro-inflammatory cytokines, such as IL-1β, during COVID-19." (PMID 35095880, 2021). "Platelet inflammasome NLRP3 activation is reported to trigger platelet aggregation, endothelial dysfunction, and thrombosis, which may serve as contributing factors to hypercoagulopathy, an issue that requires further investigation in COVID-19 patients." (PMID 33923537, 2021). "Colchicine may also be utilized to treat COVID-19 as a major inhibitor of NLRP3 inflammasomes, and, based on these perspectives, several RCTs are being conducted to assess the potential of colchicine to improve outcomes in patients with COVID-19." (PMID 34959657, 2021). "Based on this observation, COVID-19 patients who have strong P2X7R function may experience NLRP3 inflammasome overactivation and subsequently a “cytokine storm”, which represents a major mechanism underlying the disease exacerbation in some but not all male patients." (PMID 34150848, 2021). "In addition to TLRs, it has been shown that curcumin can diminish NF-κB activation, as well as inhibit the NLRP3 inflammasome, which could play a significant role in the development and progression of COVID-19." (PMID 34833991, 2021). "Therefore, testosterone therapy may improve the clinical outcomes in COVID-19 patients through NLRP3 inflammasome/NF-κB-dependent activation of anti-inflammatory cytokines and suppression of pro-inflammatory cytokines." (PMID 34568081, 2021). "A recent study demonstrated that male COVID-19 patients had higher plasma levels of innate immune cytokines, such as IL-8 and IL-18, along with more robust induction of non-classical monocytes, suggesting that sex difference is a major factor affecting the activation of NLRP3 inflammasome." (PMID 34150848, 2021). "Additionally, hyper-activation of NLRP3 may result in coagulopathy, neutrophil infiltration, Th17 and macrophage activation and a cytokine storm in severe COVID-19 patients." (PMID 33643932, 2021). "Hence, targeting NLRP3 inflammasome may be an effective strategy for the treatment of severe COVID-19 patients." (PMID 34150848, 2021). "While treating cardiovascular complications by targeting NLRP3 pathway components clearly provides new opportunities in drug development, further studies and clinical trials are required to validate safety and efficacy of the therapeutic compounds in COVID-19 patients." (PMID 33923537, 2021).
COVID-19 (continued). "Moreover, NLRP3 is known to coordinate this uncontrolled inflammatory response, and, for this reason, its possible inhibition can be considered as a novel target to develop COVID-19 supportive therapies." (PMID 34564408, 2021). "Moreover, monocytes infected in vitro with SARS-CoV-2 presented the formation of NLRP3 puncta, and the same could be observed in mononuclear cells isolated from COVID-19 patients, indicating activation of the inflammasome pathway." (PMID 33193377, 2020). "Taking together, the known effects of coronavirus proteins on NAD+, NLRP3, and the two stages of inflammasome activation, these data provide a plausible explanation as to why co-morbidities positively correlate with cytokine storms and fatality in COVID-19 patients." (PMID 32470948, 2020). "Based on this strong inflammatory potential of the NLRP3 inflammasome in the context of infections caused by SARS-CoVs, it appears to be an important druggable target, and its inhibition can potentially reduce tissue inflammation, also in the context of COVID-19." (PMID 32574259, 2020). "Activation of the NLRP3 inflammasome in response to SARS-CoV-2 infection has been observed in postmortem samples and peripheral blood mononuclear cells from COVID-19 patients." (PMID 40788382, 2025). "Postmortem human COVID-19 brains contained TMEM119+ microglia co-expressing viral antigens, ACE2, and NLRP3, while infection of K18-hACE2 mice induced NLRP3 upregulation in brain tissue." (PMID 41305454, 2025). "Previous research indicated that the NLRP3 inflammasome was activated in response to SARS-CoV-2 and persisted in COVID-19 patients." (PMID 40906404, 2025). "First, we looked at the expression of NLRP3 inflammasome pathway related genes in nasopharyngeal swabs (GSE152075), whole blood (EGAS00001004503), and leukocytes (GSE157103) of COVID-19 patients." (PMID 38748756, 2024). "Experiments performed with NLRP3-deficient mice support our assertion that NLRP3 inflammasome indeed participates in the genesis of the inflammatory process observed during COVID-19, as opposed to the hypothesis that NLRP3 is only an additional marker of inflammation." (PMID 38838044, 2024). "Lower inflammasome pathway activation was observed with significantly lower gene and protein expression of NLRP3, cleaved caspase-1, ASC and IL-1β among severe COVID-19 patients treated with VitD3." (PMID 38748756, 2024). "A significant increase in NLRP3 and caspase-1 expression was observed in HPMVEC treated with COVID-19 serum compared to those treated with healthy serum." (PMID 38771750, 2024). "Nonetheless, a significant decrease in plasma levels of key NLRP3 inflammasome markers, specifically NLRP3, caspase-1, and GSDM-D, was observed in COVID-19 patients who received a 10-day diacerein treatment compared to those who received placebo." (PMID 39434905, 2024). "Lung tissues from patients with COVID-19 were shown to contain NLRP3 and ASC puncta, confirming that the NLRP3 inflammasome is indeed activated in infected patients with acute lung injury." (PMID 38390874, 2024). "It is well established that the multiorgan failure and death in COVID-19 patients are due to the hyperactivation of the NOD-, LRR- and pyrin domain-containing protein 3 (NLRP3) inflammasome and the ensuing cytokine storm." (PMID 39070405, 2024). "More recently, it has been proposed that inhibiting the inflammasomes pathways and/or pyroptosis in COVID-19 therapy would be an efficient strategy to decrease SARS-CoV-2 virulence and NLRP3-mediated inflammation for treatment of severe COVID-19 disease." (PMID 36800238, 2023). "Pharmacological inhibition of the NLRP3 inflammasome upon SARS-CoV-2 infection can suppress immune overactivation and alleviate COVID-19 in preclinical mice models." (PMID 36316366, 2023).
COVID-19 (continued). "Given the similar NLRP3 inflammasome activation and reactivation profiles observed in both ICU COVID-19 patients and those with bacterial septic shock, we combined the two cohorts for survival analyses." (PMID 38140660, 2023). "IL-1β secretion is reduced when SARS-CoV-2 was preincubated and neutralized with COVID-19 patient’s serum before infection of ACE2-A549 cells, thus revealing that NLRP3 inflammasome is activated after viral entry into permissive host cells." (PMID 37920468, 2023). "Altogether, our results reveal an unexpected relationship between the purinergic receptor P2X7, the NLRP3 inflammasome and the permissiveness to SARS-CoV-2 infection that offers novel opportunities for COVID-19 treatment." (PMID 37920468, 2023). "To study the potential contribution of NLRP3 to SARS-CoV-2 pathogenesis, we first analyzed the expression of NLRP3 in lung tissue samples obtained from three uninfected individuals and seven SARS-CoV-2-infected patients who died from COVID-19." (PMID 37920468, 2023). "In this study, we first found that the gene expression of NLRP3 and IL-1β was downregulated in the CD14+ and CD16+ monocytes from COVID-19 patients, while MARCH7 and IL-18 declined only in the CD16+ monocytes." (PMID 38004809, 2023). "NLRP3 was found as an upregulated gene in SARS-COV2 affected patients and considered as a major biomarker to increase the cytokines level in the plasma of COVID-19 patients." (PMID 36949176, 2023). "The expression levels of NLRP3, NLRP6, IL-1β, and MARCH7 were decreased in COVID-19 patients, and this reflected the inhibition of the NLRP3 inflammasome pathway." (PMID 38004809, 2023). "Among the gene profiles demonstrated in this study, the SNPs of NLRP3 and IL12B were consistently defined as potential factors for specific antibody production and maintenance after COVID-19 vaccination." (PMID 37564647, 2023). "The NLRP3 inflammasome is activated during SARS-CoV-2 infection and is active in COVID-19 patients and in autopsy tissues." (PMID 36669831, 2023). "Increasing evidence has shown that NLRP3 inflammasome is activated in response to SARS-CoV-2 infection, is active in COVID-19 patients, and participates in the pathophysiology." (PMID 36851564, 2023). "Together, these studies provide clinical and mechanistic evidence that the NLRP3 inflammasome is suppressed at the early stages of SARS-CoV-2 infection and overactivated at later stages, and this could be the main cause of the cytokine storm seen in severe COVID-19 patients." (PMID 37508374, 2023). "Other NLRP3 specific inhibitors, such as OLT1177 and DFV890, are under clinical evaluation to reduce COVID-19 symptoms, early cytokine release syndrome, and respiratory function." (PMID 37515138, 2023). "As would be expected from the SARS-CoV-2 viral activation pattern just described, TLR3, TLR7, TLR8, TLR9, NLRP3, RIG-1 and MDA-5 are activated in patients with severe COVID-19." (PMID 36769320, 2023). "Given that macrophages are key cellular players for COVID-19 pathogenesis and inflammasome activation was detected in SARS-CoV-2-infected macrophages, we first analyzed the expression of NLRP3 during the infection of macrophages with SARS-CoV-2." (PMID 37920468, 2023). "Inflammation is a key feature of COVID-19, with acute SARS-CoV-2 infection and exposure to viral components shown to strongly stimulate the NLRP3 inflammasome." (PMID 37112929, 2023). "Statins inhibit NLRP3 inflammasome activation by suppressing the oxidized LDL, and TNF α, and improving the cardiovascular functional outcomes in COVID-19 patients." (PMID 35865966, 2022). "In addition, a recent clinical trial concluded that NLRP3 inflammasome activation by antibody-mediated SARS-CoV-2 in monocytes/macrophages triggers inflammatory cell death and terminates the infection but causes systemic inflammation that contributes to COVID-19 pathogenesis." (PMID 35563697, 2022).
COVID-19 (continued). "This review also highlights the role of the NLRP3 inflammasome in neurological diseases such as AD and PD/LBD, and in the pathogenesis of COVID-19 including so-called ‘long-COVID’ symptoms." (PMID 35052628, 2022). "It was shown that NLRP3 signalling is upregulated in COVID-19 lungs, together with many ‘DAMPs’ such as metabolic dysregulation and ROS that are triggered by SARS-CoV-2 and can lead to NLRP3-inflammasome-mediated pyroptosis leading to a cytokine storm." (PMID 35626754, 2022). "However, the specific role of NLRP3 inflammasome in children with COVID-19 is still unknown." (PMID 36248872, 2022). "As highlighted earlier, the NLRP3 inflammasome is a crucial mediator of inflammation and neuro-glial damage after AIS and COVID-19-mediated ischemic stroke." (PMID 35328506, 2022). "Recently NLRP3 activation and ASC speck formation in peripheral blood cells and CD14+ cells from autoptic lung tissue of patients with COVID-19 has been reported." (PMID 36096831, 2022). "In COVID-19, SARS-CoV-2 also activates both toll-like receptors (TLRs) and the NOD−, LRR−, and pyrin domain-containing protein 3 (NLRP3) inflammasome." (PMID 35639261, 2022). "Studies show that NLRP3 (NOD-, LRR- and pyrin domain-containing protein 3) inflammasome is highly expressed in patients with COVID-19, being a potential marker of disease severity." (PMID 36111789, 2022). "Molecular docking suggested that active ingredients (including: licopyranocoumarin, Glycyrol and 3-3-Oxopropanoic acid) in LHQW played a role in treating COVID-19 by acting on CSF2, CXCL8, CCR5, NLRP3, IFNG and TNF." (PMID 36506032, 2022). "The loss of cellular ion homeostasis has been proven to promote NLRP3 inflammasome activation and cell pyroptosis during SARS-CoV-2 infection, thus ion-channel inhibitors (such as Amantadine, Memantine, Rimantadine, Tretinoin197) could be utilized in treatment with COVID-19 patients." (PMID 35697684, 2022). "There are many preclinical and clinical trials targeting NLRP3 and GSDMD to treat COVID-19 patients." (PMID 35287354, 2022). "In this study, COVID-19, the crossover genes between RA and pyroptosis were enriched in the NLR/TLR signaling pathway, NLRP3 inflammasome complex, death-inducing signaling complex, regulation of interleukin production, NF-κB signaling, and TNF signaling." (PMID 36532040, 2022). "We observed a significant increase in mRNA expression of NLRP3, pro-caspase-1 (CASP1), and pro-IL-1β genes in HMEC-1 cells exposed to exosomes from the plasma of severe COVID-19 patients compared with that from healthy subjects." (PMID 35587188, 2022). "Being that inflammasome activity is dysregulated in COVID-19, following the infection, alveolar macrophages secrete TNF-α and IL-1β, giving rise to cell death, damage, and NLRP3 activation that trigger the acute proinflammatory cascade." (PMID 33916409, 2021). "Immunofluorescence analysis of the autopsy lung samples revealed higher numbers of NLRP3 and ASC speck in samples from COVID-19 patients compared to controls." (PMID 34977191, 2021). "As reviewed by Freeman and Swartz, NLRP3 has a known role in hyperinflammatory ARDS, severe MERS-COV, and SARS-CoV infection, and initial studies have indicated its involvement in severe COVID-19." (PMID 34564326, 2021). "This work thereby identifies a molecular mechanism by which SARS-CoV-2 infection causes ARDS, provides evidence that links the NLRP3 inflammasome and lung injury, and suggests that MCC950 and Ac-YVAD-cmk might function as potential therapeutic agents for the prevention and treatment of COVID-19." (PMID 34341353, 2021). "By inhibiting NF-κB-dependent pathways, um-PEA targeted and downregulated NLRP3, one of the most involved mediators in ARDS, recognized as a possible target for the pharmacological treatment in the early stages of COVID-19." (PMID 34564408, 2021).
COVID-19 (continued). "SARS-CoV, which is closely related to the SARS-CoV-2 virus responsible for COVID-19, has been shown to activate the NLR-family pyrin domain-containing 3 (NLRP3) inflammasome." (PMID 34051877, 2021). "In COVID-19, the degree of inflammasome activation, particularly the nucleotide binding domain (NOD)-like pyrin domain 3 (NLRP3) inflammasome, correlates with disease severity." (PMID 34672950, 2021). "Our data also support the use of specific NLRP3 inhibitors, such as MCC950, to attenuate inflammasome-related responses during COVID-19, since this drug was able to abrogate ex-vivo IL-1β secretion, conversely to colchicine, which decreased TNF-α release." (PMID 35095880, 2021). "Higher numbers of NLRP3 and ASC puncta have been observed in COVID-19 patients, and IL-18 and Caspase-1 p20 levels are correlated with disease severity and clinical outcome." (PMID 33912161, 2021). "Ion disturbance, mediated by virioporins, is central to the mechanism of action of a range of viruses from influenza, and rhinovirus to COVID-19 and HIV, and a number of RNA viruses modulate activity of the NLRP3 inflammasome in a potassium-dependent manner." (PMID 34778307, 2021). "In particular, in lung tissues from lethal cases of COVID-19, active inflammasomes and CD14+ cells infected by SARS-CoV-2 and expressing NLRP3 were detected." (PMID 33669011, 2021). "ROC for inflammatory markers indicated the significant role of HMGB1, NLRP3, IL-6 and ACE2 in discriminating the presence of headache in patients with COVID-19." (PMID 34384355, 2021). "So far, it is the first clinical study investigating the role of circulating inflammatory and nociceptive molecules such as HMGB1, NLRP3 inflammasome, IL-6, IL-10, angiotensin II, and ACE2 in COVID-19 headache." (PMID 34384355, 2021). "Taken together, we reveal a pathological mechanism of COVID-19, in which SARS-CoV-2 N protein promotes inflammation and lung injury via promoting the activation of the NLRP3 inflammasome." (PMID 34341353, 2021). "Furthermore, considering the clinical use of several NLRP3 inhibitor drugs for the treatment of other inflammatory diseases, controlled studies of these co-morbid patients might also determine potential usefulness of these agents in the treatment of COVID-19." (PMID 32574259, 2020). "Statins have the potential to block the molecular mechanisms, including NF-κB and NLRP3 inflammasomes and TLR signalling which are responsible for the "cytokine storm" in severe COVID-19 patients." (PMID 33060704, 2020). "Several clinical trials are currently evaluating NLRP3 inhibitors in severe COVID-19, aiming to suppress harmful hyperinflammation without compromising pathogen clearance." (PMID 40959087, 2025). "In this study, we demonstrated that EOC inhibits the NLRP3 inflammasome, suggesting that EOC may have beneficial effects on COVID-19." (PMID 40508226, 2025). "The SARS-CoV-2 N protein could directly induce the activation of the NLRP3 inflammasome, indicating that the inhibitory effect of SFN on this pathway could reduce inflammation in patients with COVID-19." (PMID 39459194, 2024). "In particular, NLRP3 and NLRP1 inflammasome activation—as well as the components of its signaling, i.e., CASP1, IL-1β, and IL-18, etc.—show a relationship with the inflammatory factors and disease progression in patients with COVID-19." (PMID 38612539, 2024). "In addition, NLR family pyrin domain-containing 3 (NLRP3) inflammasome activation is downstream of SARS-CoV2 infection, which is important in inducing inflammatory responses in patients with COVID-19." (PMID 38807598, 2024). "The low-dose colchicine used to treat COVID-19 is not sufficient to reach the necessary intracellular concentration for NLRP3 inflammasome inhibition." (PMID 38741862, 2024).